KRAS (KRas proto-oncogene, GTPase)
Diseases named in the same sentence as KRAS in open-access papers (continued):
Sharing a sentence is not in itself a finding about the gene and the disease.
cancer (continued). "Given that BAD is a vital downstream mediator of RAS effector pathways mediating cancer cell survival and apoptosis, targeting its phosphorylation may be and is demonstrated herein, to be advantageous for the treatment of KRAS-mutant PDAC." (PMID 38409090, 2024). "Studies have shown that nutrient supply is an important determinant of KRAS regulation of cancer." (PMID 38886847, 2024). "Given that KRAS inhibitor resistance is still a serious challenge in clinical practice, it remains to be elucidated in deeper detail to achieve precise therapies for cancer patients." (PMID 38763973, 2024). "However, various clinical trials have yielded disappointing results, failing to demonstrate significant survival benefits of MEK inhibition, either as a single-agent treatment or combined with chemotherapy for KRAS-mutant cancers." (PMID 38409090, 2024). "Therefore, there remains an urgent and unmet need for a better understanding of KRAS biology and innovative treatment strategies tailored to KRAS-mutant cancers." (PMID 38275900, 2024). "KRAS is notorious for being difficult-to-drug in cancer therapy." (PMID 39355533, 2024). "Consequently, understanding KRAS biology has become a focal point in developing targeted therapies and improving treatment outcomes for KRAS-related cancers." (PMID 38982514, 2024). "For decades, mutated KRAS has been recognized as an attractive drug target for treating multiple types of cancer, but the development of targeted drugs has not been as successful as anticipated." (PMID 38734764, 2024). "KRAS plays a pivotal role in promoting cancer through the activation of RAF-MAPK and PI3K pathways." (PMID 38777950, 2024). "The human KRAS gene, located on 12p12.1, has six exons and two splice variants, with KRAS4B being highly expressed and KRAS4A weakly expressed, though recent studies have shown a widespread expression of KRAS4A in cancer." (PMID 39056802, 2024). "However, a major difficulty for KRAS therapies is to limit their effects on cancer cells while minimizing their adverse effects on healthy cells." (PMID 39127751, 2024). "Moreover, targeting this pathway, such as by dasatinib, shows potential for overcoming resistance to KRAS inhibitors and improving outcomes for patients with KRAS-mutant cancers." (PMID 39704172, 2024). "KRAS, located downstream of many cell surface receptors, is a central regulator of intracellular signaling in response to extracellular stimuli, making it crucial for regulating diverse cancer cell activities, including stemness." (PMID 39061234, 2024). "Indeed, abundant research underscores the substantial impact of the PI3K/AKT pathway on the response of KRAS-mutant cancer to MEK inhibition and the efficacy of concurrently targeting both the MAPK and PI3K/AKT signaling pathways has been demonstrated." (PMID 38409090, 2024). "Thus, the results of our studies provide new opportunities for developing an optimal therapeutic approach to the treatment of KRAS mutant cancers applying high doses of D-VC in combination with ATO." (PMID 38473779, 2024). "Mutations in the RAS family, genes NRAS, KRAS, and HRAS are prevalent across various cancers." (PMID 39199633, 2024). "While activating mutations in KRAS have been studied extensively in low-grade serous and other cancers, in HGSC the activating mutations are almost non-existent and the role of wtKRAS has been less explored." (PMID 38317080, 2024).
cancer (continued). "For example, some drugs could only exert effects in a small subset of KRAS mutant cancers, and it is hard to balance between efficacy and toxicity." (PMID 38706597, 2024). "The therapeutic approach in NSCLC depends on the presence or absence of specific mutations, which in this type of cancer occur most frequently in the EGFR or KRAS gene." (PMID 39457707, 2024). "Therefore, the search for new methods and strategies for the treatment of KRAS mutant cancers is a critical area in oncology." (PMID 38473779, 2024). "In this study, we showed that dual inhibition of SUMOylation and MEK could conquer MYC-expressing KRAS-mutant cancers by complementarily enhancing DNA damage accumulation." (PMID 38992694, 2024). "Tested for different types of KRAS mutated cell lines of pancreatic cancer [MIAPaCa-2 (G12C), MOH (G12R), PANC-1 (G12D)], and colon cancer [SW116 (G12A), SW948 (Q61L)], which observed significant inhibition of proliferation of cancer cells." (PMID 39056802, 2024). "This discovery suggests that these metabolites could serve as potential biomarkers detectable in KRAS-mutant cancer cells." (PMID 38672219, 2024). "Collectively, these findings demonstrate that diverse, KRAS-mutant cancer cells undergo large-scale transcriptional changes during sustained ERK/MAPK inhibition, yet the transcriptional programs associated with terminal resistance are heterogenous and model-specific." (PMID 38822082, 2024). "Future endeavors should aim to bridge the existing gaps in knowledge, with a particular focus on unraveling the complexities of the TME and exploring novel combinations of therapeutic modalities to improve patient outcomes in the fight against KRAS-mutant cancers." (PMID 39252322, 2024). "Important hallmarks of cancer terms include KRAS signaling up and IL-6/JAK/STAT3 signaling." (PMID 38627442, 2024). "Our finding that KRAS-driven mechanisms maintain cellular growth and immunosuppression of both adaptive and innate immunity, highlights future therapeutic strategies that should consider a combination of KRAS cancer-targeting therapy with strategies targeting both T cells and myeloid cells." (PMID 38727236, 2024). "In contrast, the analysis for KRAS exon 13 revealed no mutations in any of the cases, which reinforces the distinct pathophysiological trajectories in cancer." (PMID 38390896, 2024). "It is also worth investigating whether KRAS ubiquitination is getting dysregulated during cancer progression, to identify mechanisms of this dysregulation and its contribution to RAS-driven cancers." (PMID 38858602, 2024). "Interestingly, the upregulation of miR-622 induced by resveratrol was found to downregulate KRAS (a potent oncogene in lung cancer) expression, and partially inhibit cancer cell proliferation." (PMID 38972997, 2024). "In vitro studies have also shown that divarasib is 5 to 20 times as potent and up to 50 times as selective compared to the KRAS G12C inhibitors sotorasib and adagrasib (Purkey, H. Discovery of GDC-6036, a clinical stage treatment for KRAS G12C-positive cancers." (PMID 39125664, 2024). "In this study, we observed that cancer cells resistant to KRAS G12C inhibitors also display cross-resistance to other targeted therapies such as inhibitors of epidermal growth factor receptor (EGFR), insulin-like growth factor 1 receptor (IGF1R), MEK, PI3K, or SHP2." (PMID 39704172, 2024). "Further, it also indicates that KRAS signaling may have different consequences in varying cancer types, which can be correlated to the variation in the expression of cancer-stimulating neoantigens." (PMID 39057088, 2024). "This suggests that CAFs might be key players in independently modulating cancer cell phenotypes in the context of KRAS-targeted therapies." (PMID 39061234, 2024).
cancer (continued). "This suggests that the oncogenic drivers may influence the pathway for de novo polyamine synthesis, with MYC-driven cancers potentially preferring arginine as a precursor and KRAS-driven cancers preferring glutamine." (PMID 38761252, 2024). "With all these data taken together, CD44 could represent a potential therapeutic target for treating KRAS-dependent carcinomas." (PMID 38672650, 2024). "Other KRAS inhibitors are on the way to block KRAS-mutant cancers." (PMID 37662925, 2023). "This implies that CERS4 expression was reduced in the KRAS mutation group, potentially resulting in a diminished proapoptotic effect, may be why low-CERS4 cancers had more venous invasion." (PMID 37758931, 2023). "Therefore, KRAS dependency is so essential in KRASmu PDAC that cancer cells have secured several compensatory escape mechanisms to counteract the efficacy of KRAS inhibitors, such as activation of MEK/ERK signaling or YAP1 upregulation." (PMID 37298264, 2023). "The KRAS gene has been proven to be one of the most common carcinogenic drivers of human cancer." (PMID 37468609, 2023). "Protective autophagy in KRAS-mutant cancers is an attractive target for PDAC." (PMID 37996408, 2023). "While the development of targeted immunotherapies has led to a substantial improvement in the overall survival of patients with non-KRAS-mutant cancer, patients with RAS-mutant cancers have an overall poorer prognosis owing to the high aggressiveness of RAS-mutant tumors." (PMID 37662925, 2023). "Based on the findings of this study, it can be inferred that these compounds may have the potential to be employed in the treatment of cancer by targeting KRAS." (PMID 37822837, 2023). "As expected, TUS-007 could respond selectively to cetuximab-resistant SW620 cancer cells with KRAS (G12V) as a driver." (PMID 37513471, 2023). "Hence, considering the emerging significance of ferroptosis in cancer and its potential interplay with KRAS signaling, an in-depth analysis of changes in ferroptosis-associated pathways is warranted." (PMID 38268915, 2023). "Thus, KRAS dependency is so strong and essential in KRASmu PDAC that cancer cells have secured several compensatory escape mechanisms to counteract the effectiveness of KRAS inhibitors." (PMID 37298264, 2023). "In line with the fact that KRAS influences cell proliferation in various cancers, we hypothesized that HIF1A-As2 may participate in lung tumorigenesis." (PMID 37041291, 2023). "It is possible that combination of tunlametinib with SPH2 inhibitor could potentially confer a beneficial outcome for wide-type KRAS-amplified cancers and could have therapeutic utility in multiple cancers." (PMID 37808191, 2023). "We tested whether the cyclo-CRVLIR peptide, as well as the other cyclo-CRVLAA 2nd derivatives (cyclo—CRVLID, CRVLRD, CRVLRR, CRVLKR, CRVLTR, CRVLKD), would be able to inhibit the p110α/KRAS interaction in cancer cell lines." (PMID 36732563, 2023). "Interestingly, a growing body of evidence coincides with the notion that the RAF family, particularly CRAF, assumes a pivotal role in oncogenic KRAS-driven cancers." (PMID 38111008, 2023). "KRAS-mutant cancer cells are known to demonstrate high levels of basal autophagy and thus might be more vulnerable to autophagy inhibition." (PMID 37402770, 2023). "Oncogenic KRAS mutation, the most frequent mutation in non-small cell lung cancer (NSCLC), is an aggressiveness risk factor and leads to the metabolic reprogramming of cancer cells by promoting glucose, glutamine, and fatty acid absorption and glycolysis." (PMID 38093368, 2023). "Moreover, loss of REDD1 in KRAS mutant NSCLC not only increases FAO, but also allows cancer cells to cope with increased reactive oxygen species (ROS) by boosting ROS detoxifying systems." (PMID 36675307, 2023). "Furthermore, KRAS-driven cancers are notoriously difficult to treat and close to 50% of all CRC cases are characterized by mutated KRAS." (PMID 36803614, 2023).
cancer (continued). "A study found that regulating ROS or inhibiting fibroblasts growth factor receptor 1 (FGFR1) signaling could abrogate the immunosuppression mediated by PD-L1, improving the efficacy of immunotherapy in KRAS-mutant cancers." (PMID 36675641, 2023). "Nevertheless, this study is considered preliminary, and future studies to validate the anti-cancer prophylactic and therapeutic efficacy of the live recombinant L. lactis secreting KRAS can be further validated in pre-clinical disease challenge studies with a significantly larger sample size." (PMID 37240273, 2023). "Moreover, the expression of glucose transporter 1 (GLUT1) can be regulated by KRAS to promote glycolytic metabolism in cancer." (PMID 35616307, 2023). "This central position to orchestrate hallmarks of life may explain why RAS is so frequently exploited in cancer, where the three RAS genes, KRAS, NRAS and HRAS combined are mutated in 19% of cancer patients." (PMID 36688434, 2023). "KRAS mutations are frequently linked to resistance to targeted medicines and poor outcomes in cancer patients, yet after more than three decades of research, no selective KRAS inhibitor has been authorized." (PMID 36865574, 2023). "Recent studies have shown that second generation epidermal growth factor receptor (EGFR) inhibitors may also be used to treat KRAS-mutant cancers such as NSCLC." (PMID 36674513, 2023). "SPH2/MEK inhibitor combinations prevent adaptive resistance in KRAS mutant cancer model." (PMID 37808191, 2023). "Several types of NPs have been explored for cancer treatment, including in the development of new anti-KRAS therapies, such as liposomes, solid lipid nanoparticles, dendrimers, polymeric micelles, polymeric nanoparticles, inorganic particles, and extracellular vesicles." (PMID 37376135, 2023). "Our profiling of plasma eccDNA from 16 Stage III‐IV PDAC patients and 19 healthy controls for the detection of cancer pathogenic SNP in eccDNA did not reveal any KRAS‐derived eccDNAs or eccDNAs with pathogenic variants in the samples from either group." (PMID 37602814, 2023). "Furthermore, there also lies the possibility of exploiting the altered metabolism of KRAS-mutant cancers against themselves." (PMID 37190303, 2023). "KRAS is the most commonly mutated gene in PDAC, and its mutation could activate a series of downstream oncogene signalling, inducing cancer genesis, progression and metastasis." (PMID 38037549, 2023). "Indeed, numerous studies have demonstrated the therapeutic benefits of combining KRAS inhibitors with ICB in KRAS-mutant mouse cancer models." (PMID 37581538, 2023). "Furthermore, KRAS mutant cancer cells produce inflammatory lipid mediators, establishing an inflammatory microenvironment." (PMID 36675307, 2023). "KRAS was determined to deregulate the glycolytic pathway and its components in KRAS-driven cancers." (PMID 37110218, 2023). "Therefore, simultaneous targeting CRAF and MEK1/2 is highly anticipated as a strategy to treat KRAS mutant cancers." (PMID 36872366, 2023). "Furthermore, interestingly, several previous studies demonstrated Andro’s biological properties in RAS-transformed cancer cells, suggesting Andro’s promising potential against PDAC, where more than 90% have mutations of KRAS." (PMID 36672630, 2023).
cancer (continued). "This study evaluated survival benefit with different 1L and 2L therapies in patients with KRAS G12C or WT cancer with or without STK11 and/or KEAP1 mutations, providing additional insights into these frequently co-occurring mutations." (PMID 37069542, 2023). "The observation in cancer databases of preferential amplification of KRAS versus HRAS or NRAS might seem counterintuitive if it is already the most abundant isoform." (PMID 36864243, 2023). "For example, activating mutations in KRAS, BRAF, and PI3KA, commonly detected in many cancers, may play a role in immune escape through the upregulation of programmed cell death ligand-1 and immunosuppressive cytokines." (PMID 37190307, 2023). "Moreover, neo-mutations in endometriotic epithelial cells of two cancer-driver genes, ARID1A and KRAS, would favor their diffusion." (PMID 36979957, 2023). "However, accumulating evidence suggested that KRAS mutant cancer cells bypass sensitivity to SCD inhibition by scavenging unsaturated fatty acids from lysophospholipids." (PMID 36675307, 2023). "Therefore, investigating the distinct roles of KRAS mutant alleles in the context of the tissue of origin is crucial to developing effective treatment strategies for KRAS-dependent cancers and to create tissue-specific applicability of KRAS inhibitors." (PMID 37020035, 2023). "Thus, our results and those of others point at MYC downregulation as a means to achieve an optimal antitumor response in KRAS-driven cancers." (PMID 37816716, 2023). "The close link between KRAS signaling and lipid metabolism suggests that targeting lipid metabolism may be an effective strategy for the treatment of KRAS-driven cancers." (PMID 38020549, 2023). "Perturbing SOS1 activity can in turn disrupt KRAS signaling and, therefore, an SOS:Grb2 PPI inhibitor may play an important role in a drug combination strategy for the treatment of KRAS mutant driven cancers." (PMID 37108538, 2023). "Consequently, ferroptosis-inducing therapy should be combined with FSP1 inhibitors for efficient therapy of KRAS-mutant cancers." (PMID 36443441, 2023). "This is also consistent with the highly biased pattern of KRAS amplification in cancer compared to the other isoforms, suggesting higher levels of KRAS are more often hitting the sweet-spot, whereas amplification of the other isoforms remains insufficient in most contexts." (PMID 36864243, 2023). "Recent studies have shown the interplay between fatty acids and KRAS mutant cancers." (PMID 37649607, 2023). "Herein, we use physics-based simulations and experimental biophysical validation to bring new and uniform information across a broad landscape of 86 KRAS mutations observed in cancer and non-cancer diseases." (PMID 37841325, 2023). "The variant alleles of rs8720 and rs12587 are probably located in the target sites of cell recognition and modulation and, consequently, may influence the imbalance of KRAS and the survival of cancer cells." (PMID 37566020, 2023). "Unlike some other cancers linked to the KRAS gene, CLL is associated with a gene called RRAS2, which is overly active but not mutated." (PMID 38136362, 2023). "In cancer, KRAS activation has been shown to trigger inflammasome activation." (PMID 37487005, 2023).